CSMD1 (CUB and Sushi multiple domains 1)
Diseases named in the same sentence as CSMD1 in open-access papers (continued):
Sharing a sentence is not in itself a finding about the gene and the disease.
head and neck cancer (5 papers, 2005 to 2019). A primary or metastatic malignant neoplasm affecting the head and neck. "This agrees with other studies that have reported an association between loss of the 8p23 region or CSMD1 and poor survival and high stage disease in prostate, bladder and head and neck cancer patients." (PMID 30545040, 2018). "Studies have shown that CSMD1 loss is a common phenomenon in breast, lung, prostate, and head and neck cancers." (PMID 27756250, 2016). "Although the genetic alteration of CUB and Sushi multiple domains 1 (CSMD1) is known to be associated with poor prognosis in several cancers, there is a lack of clinical relevance in head and neck cancer." (PMID 30545040, 2018). "To test this hypothesis, we surveyed 32 head and neck cancer cell lines for CSMD1 promoter methylation using the Combined Bisulfite Restriction Analysis (COBRA) technique described by Xiong and Laird." (PMID 16153303, 2005).
nicotine dependence (5 papers, 2012 to 2021). Physical and psychological dependence on nicotine. "In the initial dataset, two SNPs, rs6570989 and rs2930357, located in genes GRIK2 and CSMD1, are found to be significantly associated with the progression of nicotine dependence (ND)." (PMID 24986733, 2014). "The empirical data applications to nicotine dependence also identified two genes, GRIK2 and CSMD1, joint associated with the progression of nicotine dependence." (PMID 24986733, 2014). "CSMD1, a tumor suppressor gene, is a known candidate for nicotine dependence." (PMID 26289589, 2015).
prostate carcinoma (5 papers, 2014 to 2026). A carcinoma that arises from epithelial cells of the prostate gland. "CSMD1 is one of several genes that are typically overexpressed in monocytes in prostate cancer and has been suggested as a biomarker differentiating prostate cancer from benign prostatic hyperplasia." (PMID 41516419, 2026). "Additionally, reduced CSMD1 gene expression was associated with poor prognosis in HNSCC and prostate cancer." (PMID 36553598, 2022).
psoriasis (5 papers, 2015 to 2020). An autoimmune condition characterized by red, well-delineated plaques with silvery scales that are usually on the extensor surfaces and scalp. "In an analysis of 4,122 psoriasis cases and 3,101 healthy controls, CSMD1 showed evidence of association with cigarette smoking." (PMID 33033484, 2020). "In a study of psoriasis, for which smoking is a risk factor, CSMD1 variants were found to be associated with smoking and psoriasis in an interactive fashion." (PMID 29675039, 2018). "Several studies have previously proved the association between candidate genes involved in metabolic pathways of acitretin and the pathogenic mechanism of psoriasis, such as CSMD1, CCHCR1, GLI1, SFRP4 etc.." (PMID 28146080, 2017).
Alzheimer disease (4 papers, 2017 to 2025). A progressive, neurodegenerative disease characterized by loss of function and death of nerve cells in several areas of the brain leading to loss of cognitive function such as memory and language. "Other CSMD1 SNPs were also reported to be associated with cognitive and memory functions in healthy Norwegians, with cognitive decline in Alzheimer's disease in patients of European descent, as well as with clinical outcomes of SZ in Japanese." (PMID 29379655, 2017). "Association of CSMD1 variants with Alzheimer's disease probably suggests that some part of genetic susceptibility at this locus may appear in the older age, compared to SZ susceptibility variants, but may be expressed in earlier preclinical stages as markers of cognitive and memory performance." (PMID 29379655, 2017). "Another intronic variant in CSMD1, rs2616984, was associated with cognitive performance in European GWAS and recently was found as susceptibility marker for both SZ and Alzheimer's disease in Russians, but not in Central Asian Kazakh population." (PMID 29379655, 2017).
Cognitive impairment (4 papers, 2015 to 2022). Abnormal cognition is characterized by deficits in thinking, reasoning, or remembering. "Common genetic variation within CSMD1 has been credibly associated with SZ in recent GWAS meta-analyses, and implicated in human cognitive impairment as well as reduced brain functional activation." (PMID 35532796, 2022). "Increased frequencies of CSMD1 copy number variants are reported in individuals with mild cognitive impairment and with dementia." (PMID 26171607, 2015). "CSMD1, PPP3CB, METTL7A, and KLC2 have been reported to be associated with cognitive impairment or cognitive performance." (PMID 35559016, 2022).
developmental delay (4 papers, 2020 to 2025). "For instance, CA10 is implicated in bone metabolism and bone development, ASAP1 is an important candidate gene affecting the growth and body size of Tibetan sheep, and biallelic variants of CSMD1 cause developmental delay." (PMID 40128652, 2025). "Through international variant sharing, we identified inherited biallelic CSMD1 variants in eight individuals from six families of diverse ancestry who present with global developmental delay, intellectual disability, microcephaly, and polymicrogyria." (PMID 38816421, 2024). "Here, we present a cohort of individuals with biallelic missense variants in CSMD1 from seven families with features of global developmental delay (GDD), intellectual disability (ID), dysmorphic facial features, malformations of cortical development (MCD) and seizures." (PMID 38816421, 2024).
esophageal squamous cell carcinoma (4 papers, 2021 to 2023). Esophageal squamous cell carcinoma (ESCC) is a type of esophageal carcinoma (EC) that can affect any part of the esophagus, but is usually located in the upper or middle third. "Previous studies have demonstrated that CSMD1 can restrict cancer progression by inhibiting esophageal squamous cell carcinoma proliferation, epithelial-mesenchymal transition, chemotherapy resistance, and inducing immunosuppression." (PMID 37168445, 2023). "In our previous studies, we found that 23% of esophageal squamous cell carcinoma (ESCC, 7/30) cases exhibited biallelic loss and three of four ESCC cases had exonic somatic mutations in CSMD1, using whole-genome sequencing." (PMID 36291785, 2022).
Infertility (4 papers, 2019 to 2025). "We found that multiple types of genetic perturbations of CSMD1 associate with infertility traits in humans, most notably deletions within introns 1–3 of the gene." (PMID 31604923, 2019). "Csmd1-knockout males show increased rates of infertility with significantly increased complement C3 protein deposition in the testes, accompanied by severe histological degeneration." (PMID 31604923, 2019). "For WL chickens, the copy number deletion of CSMD1 and NTRK3 may be involved in the outstanding reproduction traits, because NTRK3 and CSMD1 have been reported to play crucial roles in follicle development, ovarian quality, and infertility in human and chicken." (PMID 35391799, 2022). "Furthermore, a wealth of literature shows that genetic dysregulation of complement and complement-regulating factors is a core feature of several heritable diseases beyond infertility;20,58,78–87; we therefore consider CSMD1 to also be a reasonable candidate for many of these diseases." (PMID 31604923, 2019).
lung carcinoma (4 papers, 2013 to 2021). "Although the current evidence can not support the regulation relationships between CSMD1 and FGG, it has been reported that the expression of FGG changed during EMT of lung cancer by several genes such as FOXA1 knockdown in A549 cells." (PMID 28959347, 2017).
breast tumor (3 papers, 2016 to 2025). "Low expression of CSMD1, a tumor suppressor gene, is significantly associated with higher breast tumor grades." (PMID 41149035, 2025). "This analysis revealed that her metachronous bilateral breast tumors had the same GATA3 and CSMD1 mutations." (PMID 32833091, 2020). "We found that human breast tumor tissues expressed CSMD1 at lower levels compared to that in normal mammary tissues." (PMID 27764775, 2016).
cervical cancer (3 papers, 2021). A primary or metastatic malignant neoplasm involving the cervix. "Our study also revealed that one integration site (chr8:4915392-HPV35:6168) in the cervical cancer tissue sample is located in a previously identified tumor suppressor gene CSMD1." (PMID 35058971, 2021). "Some hotspot genes (e.g., KLF5, LRP1B, and KLF12) have previously been described in cervical cancer, and others (e.g., CADM2, CEP19, CSMD1, and NRROS) are reported for the first time in the present study." (PMID 34885212, 2021).
COVID-19 (3 papers, 2022 to 2024). A disease caused by infection with severe acute respiratory syndrome coronavirus 2. "Notably, a polymorphism in CSMD1 (rs2924725) affects COVID-19 hospitalization risk differently in females and males." (PMID 39152463, 2024). "After comparing the significant genes in T2D and COVID-19, five genes were found to be shared between T2D and COVID-19: PTPRD, CSMD1, MAGI1, ASIC2, DAB1." (PMID 36482905, 2022). "Further, in our gene-based analysis, five genes (DAB1, ASIC2, MAGI1, CSMD1 and PTPRD) were shared between T2D and COVID-19." (PMID 36482905, 2022).
glioblastoma (3 papers, 2012 to 2022). The most malignant astrocytic tumor (WHO grade IV). "This idea of diminished CSMD1 expression has previously been demonstrated in glioblastoma stem cell lines compared to its normal neuronal stem cell counterpart." (PMID 23505554, 2013). "Since miR-10a and miR-10b are both up-regulated in glioblastoma stem cells relative to neural stem cells, we next examined the expression of CSMD1 in both cell types." (PMID 22558405, 2012). "Dramatic reduction of CSMD1 mRNA expression was detected in glioblastoma stem cells by RT-PCR analysis, compared to neural stem cells, consistent with the observation that CSMD1 expression is repressed by miR-10." (PMID 22558405, 2012). "By using Targetscan algorithm, we identified CUB and SUSHI multiple domain protein 1 (CSMD1) as a candidate target for miR-10a and miR-10b, the most highly up-regulated miRNAs in glioblastoma stem cells in our profiling analyses." (PMID 22558405, 2012). "One previous study showed overexpression of miR-10a and miR-10b in glioblastoma stem cells and normal neural stem cells and both miR10a and miR-10b could repress CSMD1 expression." (PMID 36291785, 2022). "Together, these results suggest that miR-10 targets the expression of tumor suppressor genes, CSMD1 and HOXD10, in glioblastoma stem cells." (PMID 22558405, 2012).
Intellectual disability (3 papers, 2023 to 2025). "Whole-exome sequencing (WES) analysis identified two genetic variants, c.5315T>C and c.8095A>G, in the CSMD1 gene in compound heterozygosity in an individual presenting with moderate intellectual disability, anxiety disorder, obsessive–compulsive personality traits, and facial dysmorphisms." (PMID 40362533, 2025).
malaria (3 papers, 2021 to 2024). Malaria is a serious and sometimes fatal disease caused by a parasite that commonly infects a certain type of mosquito which feeds on humans. "Genes with top scores encode for different malaria relevant functions such as regulation of inflammation (CSMD1), neural adhesion (CNTN4, PCSK5, CDH13, TMEM132), vascular epithelial development (FLT4), and protein kinases (PTPRT, PRKG1)." (PMID 34868193, 2021). "Similarly, CSMD1 and the HBE1, HBG2 and HPSE2 genes were identified as candidates for positive selection in both NA and WEA populations, probably because of the historical presence of malaria in both Sub-Saharan Africa and the Mediterranean region as a common selective pressure." (PMID 37210386, 2023).
metabolic syndrome (3 papers, 2013 to 2023). A cluster of metabolic risk factors for CARDIOVASCULAR DISEASES and TYPE 2 DIABETES MELLITUS. "The presence of weight gain and altered glucose tolerance in Csmd1 KO mice is consistent with the strong association of CSMD1 to the body-mass-index and measures of the metabolic syndrome in the large Framingham Heart Study." (PMID 24244513, 2013). "Furthermore, Csmd1 KO mice also displayed increased weight-gain and glucose tolerance, similar to a major phenotype of the metabolic syndrome that also has been associated to the human CSMD1 locus." (PMID 24244513, 2013).
microcephaly (3 papers, 2021 to 2024). A congenital or acquired developmental disorder in which the circumference of the head is smaller than normal for the person's age and sex. "Of three probands with CSMD1 enhancer DNMs, two showed delayed speech and language development, delayed motor development, microcephaly, and seizures." (PMID 36854624, 2023). "In particular, ARHGEF10 is involved in neuronal morphogenesis and DECIPHER Patient 368323, which carries an ARHGEF10 SNV, presents microcephaly; CSMD1 and KBTBD11 are brain-specific expressed genes, and CSMD1 is also dosage-sensitive." (PMID 33925474, 2021). "In summary, this biallelic CSMD1 cohort exhibits shared clinical phenotypes with variable expressivity of GDD, moderate-to-severe ID, structural brain defects, musculoskeletal features, and craniofacial anomalies, and microcephaly." (PMID 38816421, 2024).
squamous cell carcinoma (3 papers, 2005 to 2021). A carcinoma arising from squamous epithelial cells. "Furthermore, other important genes related to cancer treatment including CSMD1 (potential suppressor of squamous cell carcinomas), BRIC6 (apoptosis-associated gene), and ROS1 (the member of tyrosine kinase insulin receptor genes) were more enriched in this study." (PMID 34368001, 2021). "In this paper, we demonstrate that while most squamous cell carcinoma cell lines do not express full length CSMD1 transcripts, nearly all produce abnormal transcripts unlikely to encode functional CSMD1 proteins." (PMID 16153303, 2005). "It was found that in 2,616 coding genes, 2 or more integration sites presented among samples, like RAD51B, MACROD2, FHIT, CSMD1, LRP1B, and DLG2, which had already been previously reported as frequent sites of integration in squamous carcinoma samples." (PMID 33810183, 2021).
acute myeloid leukaemia (2 papers, 2020 to 2022). "This analysis showed that CSMD1 expression was significantly increased in acute myeloid leukaemia (AML), liver, pancreas, skin, thyroid, and uterine corpus (EC) endometrial carcinoma compared to controls." (PMID 36553598, 2022).
autoimmune disease (2 papers, 2013 to 2022). A disorder resulting from loss of function or tissue destruction of an organ or multiple organs, arising from humoral or cellular immune responses of the individual to their own tissue constituents. "The precise role of CSMD1 in immune responses awaits further elucidation, while a possible association of CSMD1 in autoimmune disease (neonatal lupus) has been reported." (PMID 36553598, 2022). "Although a possible relevance of CSMD1 has been reported in autoimmune disease (neonatal lupus), the precise role of CSMD1 in immune responses remains to be further described." (PMID 24244513, 2013).
carcinoma of the ovary (2 papers, 2021). "CSMD1 has been shown to inhibit the deposition of complement factors C3b and C9 on ovarian cancer cells and promote the degradation of C3b, thereby potentially inhibiting an antitumour immune response." (PMID 33506581, 2021). "Similarly, the variant rs1482207 in CSMD1 (CUB And Sushi Multiple Domains 1) gene, another tumor suppressor gene that is frequently deleted in several cancers including HNSCC, and carcinoma of the ovary, breast and prostate, was also associated with persistent HPV16 infection in this study." (PMID 34683414, 2021).
colorectal tumors (2 papers, 2013 to 2015). "The top ranked genes, PTPRT and CSMD1, which are unique to 1CT7 and A1309 cells, respectively, have previously been reported to be mutated in colorectal tumors." (PMID 25923178, 2015). "Using 454FLX sequencing and confirming with Sanger sequencing, 16 CSMD1 somatic mutations were identified in 6 of the 54 colorectal tumors (11%)." (PMID 23505554, 2013). "Fifty-one percent (19/37) of the colorectal tumors were unbalanced at two or more contiguous CSMD1 loci, indicating that CSMD1 loss of heterozygosity could have occurred in these tumors." (PMID 23505554, 2013). "However, the high NS/S ratio of CSMD1 mutations alone highlights the importance of this gene during colorectal tumor development." (PMID 23505554, 2013). "Sanger-validated somatic mutations of CSMD1 in colorectal tumors." (PMID 23505554, 2013). "We sequenced the CSMD1 coding regions in 54 colorectal tumors using the 454FLX pyrosequencing platform to interrogate 72 amplicons covering the entire coding sequence." (PMID 23505554, 2013). "Deep amplicon sequencing and methylation-specific PCR reveal that CSMD1 alterations can correlate with earlier clinical presentation in colorectal tumors, thus further implicating CSMD1 as a tumor suppressor gene." (PMID 23505554, 2013). "Although it is impossible to query the methylation status of CSMD1 within the stem cells that gave rise to the tumors, we obtained direct evidence that CSMD1 remains heavily methylated in developed colorectal tumors." (PMID 23505554, 2013). "Finally, we performed methylation-specific PCR on 76 colorectal tumors to determine DNA methylation status for CSMD1 and known methylation targets ALX4, RUNX3, NEUROG1, and CDKN2A." (PMID 23505554, 2013).
diabetes (2 papers, 2021 to 2023). "There are in the human genome 448 genes that contain one or more clusters, and 24 genes that contain more than two clusters, reaching a maximum of nine clusters in the diabetes-related PTPRN2 and the potential tumor suppressor CSMD1." (PMID 33741065, 2021).
generalized epilepsies (2 papers, 2024 to 2025). "Also, as recently documented, CSMD1 has been described as a causative gene of developmental and epileptic encephalopathy and generalized epilepsies." (PMID 40362533, 2025).
Insulin resistance (2 papers, 2009 to 2017). Increased resistance towards insulin, that is, diminished effectiveness of insulin in reducing blood glucose levels. "Three of the GWAS genes (SLC2A9, CACNA1D and CSMD1), one in the chromosome 12 and two in the chromosome 16 synteny groups, harboured SNPs significantly associated with both blood pressure and insulin resistance/type 2 diabetes in humans." (PMID 28130354, 2017). "Three genes, SLC12A9 (chromosome 12), CACNA1D and CSMD1 (chromosome 16), were associated with both blood pressure and insulin resistance-related metabolic traits." (PMID 28130354, 2017). "CSMD1 encodes the cub and sushi domains 1 protein and, as for CACNA1D, SNPs in this gene are associated with insulin resistance in African Americans, and with blood pressure in the Han Chinese population." (PMID 28130354, 2017).
invasive ductal breast carcinoma (2 papers, 2013 to 2015). The most common type of invasive breast carcinoma, accounting for approximately 70% of breast carcinomas. "Moreover, decreased CSMD1 expression has been associated with high tumour grade and the poor survival of invasive ductal breast carcinoma, and the role of CSMD1 expression as a potential BC prognostic marker has been suggested." (PMID 23967248, 2013).
lung squamous cell carcinoma (2 papers, 2017 to 2021). "We know that CSMD1 is a tumor suppressor, and a previous array-based comparative genomic hybridization (aCGH) analysis detected the loss of CSMD1 in lung squamous cell carcinomas." (PMID 28959347, 2017).
myopia (2 papers, 2018 to 2021). "The de novo mutations of CSMD1 have been reported in a Chinese family with early-onset high myopia (EOHM)." (PMID 34222226, 2021). "Among these ocular disease related or direct high myopia related genes, five genes (CSMD1, HSPG2, RPGR, SEMA4A and USH2A) have pathogenic variants in multiple patients." (PMID 30245926, 2018). "In addition to the novel mutations found in five known myopia genes (ADAMTS18, CSMD1, P3H2, RPGR, and SLC39A5), we also identified pathogenic variants in seven ocular disease genes (ABCA4, CEP290, HSPG2, PCDH15, SAG, SEMA4A, and USH2A) as novel candidate genes." (PMID 30245926, 2018).